LUCAT1 (lung cancer associated transcript 1)
Diseases named in the same sentence as LUCAT1 in open-access papers (continued):
Sharing a sentence is not in itself a finding about the gene and the disease.
tumor (continued). "Knockdown of LUCAT1 inhibited LUAD cell metastasis and glycolysis in vitro as well as tumor metastasis in vivo, while overexpression of LUCAT1 induced a promoted LUAD metastasis and glycolysis." (PMID 35646922, 2022). "Using qPCR, we analysed the expression of DCN, miR-200c and five lncRNAs (LUCAT1, MALAT1, lncTCF7, XIST, and ZFAS1) in lymph node and liver metastases in comparison to the invasive front and central part of a primary tumour." (PMID 35052821, 2022). "Analyzing of clinical data revealed that LUCAT1 expression level was positively correlated with higher rates of Lymph Node Metastasis (LNM) and advanced Tumor Node Metastasis (TNM) stage." (PMID 35646922, 2022). "In our study, LUCAT1 knockdown can hinder the invasion and migration activity of LUAD cells in vitro and inhibit tumor metastasis in vivo." (PMID 35646922, 2022). "LINC01605, SNHG20, LUCAT1, and ZNF337-AS1 had significantly high expression in tumor tissues, while MEG9, LINC01082, and DICER1-AS1 had high expression in ADJ tissues." (PMID 34544413, 2021). "LUCAT1 is highly expressed in HCC tissues, which can promote tumor cell proliferation and metastasis, and is an independent risk factor for poor survival in HCC patients." (PMID 33424932, 2020). "Of note, a number of lncRNAs with broad oncogenic (SNHG12, CASC9, LUCAT1 and PVT1) or tumor suppressor (such as TINCR) function were also identified to be differentially expressed in cSCC25–28." (PMID 32108138, 2020). "Hypoxia also induces the expression of LUCAT1 lncRNA in cancer cells, which binds PTBP1 splicing factor resulting in alternative splicing inactivation of DNA damage-related tumour suppressors." (PMID 32536347, 2020). "As the results, all lncRNAs—AC099850.3, LUCAT1, ZFPM2-AS1, and AC009005.1—displayed high expression patterns in HCC tumor tissues when compared with normal samples, which was consistent with the findings in the TCGA cohort." (PMID 33102579, 2020). "AC099850.3, LUCAT1, ZFPM2-AS1, and AC009005.1 were highly expressed in tumor tissues than normal liver tissues according to the result of the TCGA database." (PMID 33102579, 2020). "Etiology of the chronic liver disease, histopathological grading, tumor nodularity, size, AFP serum levels and time-to-recurrence (TTR) after surgery were tested against LUCAT1, CASC9 and LINC01093 expression." (PMID 30416681, 2018). "We further determined the changes in the stemness phenotypes of BC cells via single-cell tumour sphere formation assays and found that the uptake of LUCAT1-decreased exosomes did not enhanced spheroid formation by BC cells." (PMID 40025525, 2025). "A remarkable decrease in tumor weight and volume was observed in the lncRNA LUCAT1 knockdown group in comparison with negative control at day 21 post‐implantation." (PMID 31789465, 2020). "Previously, LUCAT1 was shown to interact with an array of miRNAs such as miR-375 and miR-200c Therefore, our data cannot rule out that the interaction between LUCAT1 and other miRNAs also contribute to the tumor-promoting effects of LUCAT1." (PMID 32998707, 2020). "In this study, we found that lncRNA Lucat1 expression was significantly up regulated in tumor tissues compared to matched adjacent non-tumor tissues." (PMID 29371934, 2017). "Additionally, we explored the regulatory axis of DSTN/hsa-miR-181c-5p/LUCAT1 and IGFL2-AS1 in HNSCC, which may be involved in tumor invasion and metastasis." (PMID 39896807, 2024).
tumor (continued). "Furthermore, three LncRNAs (LUCAT1, AL031985.3 and AC015908.3) expression levels in our signature were validated through qRT-PCR in a cohort of 50 pairs of HCC patient tumor samples and corresponding adjacent non-tumor samples, along with 10 samples of normal liver tissue adjacent to benign lesions." (PMID 37945918, 2023).
infection (4 papers, 2019 to 2025). The state of being infected such as from the introduction of a foreign agent such as serum, vaccine, antigenic substance or organism. "CHROMR expression was similarly upregulated by IAV and SARS-CoV-2, infection, while other lncRNAs that were tested were preferably enhanced by either IAV (BISPR, NRIR, CCR5AS) or SARS-CoV-2 (LUCAT1) infection." (PMID 40559622, 2025).
LUCAT1 also shares sentences with these, for which no sentence is quoted: oral squamous cell carcinoma (3 papers); digestive system tumors (2); anaplastic gliomas (1); cardiovascular diseases (1); chromophobe renal cell carcinoma (1); colon cancer (1); coronary heart disease (1); Crohn disease (1); diabetes (1); endometrial carcinoma (1); head and neck squamous cell carcinoma (1); heart disease (1); heart failure (1); hepatitis B infection (1); hepatoblastoma (1); Hypertension (1); inflammatory bowel disease (1); kidney cancer (1); laryngeal carcinoma (1); liver cirrhosis (1); myocardial infarction (1); ovarian tumor (1); prostate carcinoma (1); rectal adenocarcinoma (1); renal cell carcinoma (1); thyroid cancer (1).